TNF (tumor necrosis factor)
Diseases named in the same sentence as TNF in open-access papers (continued):
Sharing a sentence is not in itself a finding about the gene and the disease.
corneal neovascularization (1 paper, 2015). New blood vessels originating from the corneal veins and extending from the limbus into the adjacent corneal stroma. "Numerous studies have shown that biologics with specificity for VEGF A such as bevacizumab and ranibizumab (a recombinant antibody and an antibody fragment, respectively) or anti-tumor necrosis factor-α microantibody, are effective in the treatment of corneal neovascularization." (PMID 26664467, 2015).
coronary thrombosis (1 paper, 2025). Coagulation of blood in any of the coronary vessels. "Post-marketing surveillance showed no disproportionality signal for MI or coronary thrombosis with ustekinumab, in contrast to elevated signals observed with specific TNF-α inhibitors, such as adalimumab." (PMID 41010679, 2025). "Post-marketing surveillance showed no disproportionality signal for MI or coronary thrombosis with ustekinumab, unlike the elevated signals observed with certain TNF-α inhibitors, such as adalimumab." (PMID 41010679, 2025).
craniopharyngioma (1 paper, 2023). A benign, partly cystic, epithelial tumor of the sellar region, presumably derived from Rathke pouch epithelium. "Notably, we observed upregulation of IFNγ, IL-1, IL-6, and TNFα in craniopharyngiomas, tumors difficult to resect due to their anatomical location and critical surrounding structures." (PMID 37492101, 2023).
Crush Syndrome (1 paper, 2022). Severe systemic manifestation of trauma and ischemia involving soft tissues, principally skeletal muscle, due to prolonged severe crushing. "The expression levels of inflammatory cytokines and chemokines (e.g., TNFα, IL-6, CXCL1, CXCL2, CXCR2, CCL2) in crush syndrome were significantly suppressed in TPEN-treated group." (PMID 36114355, 2022).
cystic lymphangioma (1 paper, 2018). "We here report a rare case of acquired intraperitoneal cystic lymphangioma secondary to subtotal colectomy in a female patient with severe evolutive Crohn’s disease treated with anti-TNF alpha." (PMID 30197739, 2018). "This is the first reported case of cystic lymphangioma in a patient under anti-TNF alpha." (PMID 30197739, 2018).
cystic tumors (1 paper, 2024). "Cystic tumors exhibited higher expression of IL1B, IL6, IL10, and TNF (all P < 0.05) than non-cystic tumors." (PMID 38965454, 2024).
demyelinating polyneuropathy (1 paper, 2025). Polyneuropathy that is characterized by demyelination of axons. "Tumor necrosis factor-α (TNF-α) inhibitors can induce demyelinating polyneuropathy, but this has not been reported with ozoralizumab." (PMID 41523451, 2025).
desmoid tumor (1 paper, 2015). A desmoid tumor (DT) is a benign, locally invasive soft tissue tumor associated with a high recurrence rate but with no metastatic potential. "Hyperthermic isolated limb perfusion with TNF-α and Melphalan resulted to be an effective treatment in desmoid tumor recurrence of the limb or where resection threatens loss of function." (PMID 26056602, 2015). "Immunohistochemistry studies demonstrated that EGF, TGF-β, TNF-α, VEGF, phosphorylated SMAD2/3, COX2, and androgen receptor were significantly increased in desmoid tumors compared with healing scar tissue and quiescent fibrous tissue." (PMID 26056602, 2015).
Diplopia (1 paper, 2020). Diplopia is a condition in which a single object is perceived as two images, it is also known as double vision. "A total of 11.1% of patients (n = 2) experienced adverse events leading to treatment discontinuation: one patient reported diplopia which occurred after 14 months of anti-TNF-α therapy, while another had a worsening of vitreous inflammation and opacity after 15 months of treatment." (PMID 32069898, 2020).
drug dependence (1 paper, 2021). "Also, IL-1β levels significantly increased in the analysis of the sample MA abuse increases the level of TNF-α in the central nervous system, and the nucleus accumbens; this is closely related to drug dependence, highly expresses TNF-α mRNA and protein." (PMID 35002809, 2021).
drug-induced vasculitis (1 paper, 2025). A skin hypersensitivity reaction due to exposure to a pharmacologic substance that is characterized by raised purpuric lesions, red macules, hemorrhagic blisters and ulcerations. "Drug-induced vasculitis is another variant of AAV and is related to the use of antithyroid drugs, antibiotics, hydralazine, allopurinol, propylthiouracil, sulfasalazine, minocycline, and anti-tumor necrosis factor-α (TNF-α) inhibitors." (PMID 40520655, 2025).
duodenitis (1 paper, 2023). Acute or chronic inflammation of the duodenum. "The duodenitis rats showed significantly higher duodenal levels of myeloperoxidase, TNF-α, IL-6, malondialdehyde, and cleaved caspase-3, a significantly lower GSH level, and histopathological alterations." (PMID 37255094, 2023). "In rats with duodenitis, the concentrations of MPO, TNF-α, IL-6, MDA, and cleaved caspase-3 significantly increased while the GSH level decreased in the duodenal homogenate." (PMID 37255094, 2023).
dysautonomia (1 paper, 2023). An acute or chronic disorder, affecting the sympathetic or parasympathetic nervous system. "The pro-inflammatory cytokines found in lower concentrations were IL-12p70 in the presence of asymmetry, and IFN-gamma and TNF in the presence of dysautonomia." (PMID 37152315, 2023).
dystocia (1 paper, 2016). Slow or difficult obstetric labor or childbirth. "In cows, uterine inflammation was characterized by measurement of IL-6, IL-8, IL-1β, interferon (IFN) γ and TNF-α protein by ELISA in vaginal mucus derived from post-parturient cows presenting dystocia or eutocia." (PMID 27152525, 2016).
dystrophinopathies (1 paper, 2017). "Some of these studies showed that the functional blockade of NF-κB or the inflammatory cytokines, such as TNF-α, IL-6 and IL-1β are a specific therapeutic strategy for the treatment of dystrophinopathies." (PMID 28787441, 2017).
ectodermal dysplasia (1 paper, 2022). "In HC rat lungs at P14, the number of ectodermal dysplasia (ED)-1- and TUNEL-positive cells and level of inflammatory cytokines such as interleukin (IL)-1α, IL-1β, IL-6, and TNF-α were significantly increased." (PMID 35743045, 2022).
electrolyte disorders (1 paper, 2021). "Patients using anti-TNF agents had more IBD-related hospital days and electrolyte disorders and were more likely to undergo a colonoscopy." (PMID 33646314, 2021).
embryonal carcinoma (1 paper, 2014). A non-seminomatous malignant germ cell tumor characterized by the presence of large germ cells with abundant cytoplasm resembling epithelial cells, geographic necrosis, high mitotic activity, and pseudoglandular and pseudopapillary structures formation. "The CD30 is part of the TNF cytokines family and is used as a marker of embryonal carcinoma." (PMID 25815097, 2014).
epithelial ovarian tumors (1 paper, 2023). "Recent studies have suggested that tumor necrosis factor-α (TNF-α) promotes the expression of pro-inflammatory cytokines (IL-1β, IL-6 and TNF-α) in human epithelial ovarian tumors." (PMID 37305383, 2023).
epithelioid sarcoma (1 paper, 1996). An aggressive malignant neoplasm of uncertain differentiation, characterized by the presence of epithelioid cells forming nodular patterns. "Taken together, these data are the first showing significant antiproliferative effects in human epithelioid sarcoma by RA and TNF-alpha." (PMID 8595164, 1996). "Therefore, we investigated the effects of retinoic acid (RA) and tumour necrosis factor alpha (TNF-alpha) on tumour cell proliferation of three different clonal subpopulations (GRU-1A, GRU-1B, GRU-1C) derived from the same human epithelioid sarcoma cell line, GRU-1." (PMID 8595164, 1996).
equine diseases (1 paper, 2017). "Therefore, our finding that misoprostol significantly inhibits TNFα in equine leukocytes could support the use of misoprostol as an adjunct treatment for an array of equine diseases in which dysregulated TNFα production causes deleterious effects for the host." (PMID 29034249, 2017).
Exotropia (1 paper, 2021). A form of strabismus with one or both eyes deviated outward. "The levels of IL-6, IL-10, IL-17A, IL-12P70, INF-γ, and TNF-α were detected in tears in patients with concomitant exotropia and healthy controls matched by age and gender through the Simoa technology." (PMID 34659636, 2021). "Firstly, increased exposure and local lesions in concomitant exotropia lead to increased expression of inflammatory factors, especially IL-6 and TNF-α, in the tears." (PMID 34659636, 2021). "The concentration of tear mediators increased obviously in concomitant exotropia, and the IL-6 and TNF-α could be important mediators of inflammation." (PMID 34659636, 2021).
extrahepatic cholestasis (1 paper, 2020). Impairment of the bile flow caused by an obstruction in the portion of the bile duct system located outside of the liver. "Our analysis predicted that total Cholesterol, GGT, ALP and TNFα were the only significant biological markers with exact cut-off scores, capable of distinguishing between HCMV associated intrahepatic and extrahepatic cholestasis." (PMID 32985571, 2020).
Facial palsy (1 paper, 2023). Facial nerve palsy is a dysfunction of cranial nerve VII (the facial nerve) that results in inability to control facial muscles on the affected side with weakness of the muscles of facial expression and eye closure. "Other symptoms that developed under TNF-inhibition included progressive liver cirrhosis, most probably due to nodular regenerative hyperplasia, and peripheral facial palsy without abnormalities on MRI (both patient 1)." (PMID 37277582, 2023).
facioscapulohumeral muscular dystrophy (1 paper, 2014). An autosomal dominant disorder affecting the skeletal muscles of the face, scapula, and upper arm. "In support of this, elevated signal intensity in T2-STIR images was associated with increased immune and inflammatory cells (CD8+ T cells, IL12p40, IFNγ and TNFα) in facioscapulohumeral muscular dystrophy." (PMID 25203313, 2014).
familial hemiplegic migraine type-1 (1 paper, 2013). "Here, we investigated whether, in trigeminal sensory ganglia, cytokines such as TNFα might contribute to a local inflammatory phenotype of a transgenic knock-in (KI) mouse model of familial hemiplegic migraine type-1 (FHM-1)." (PMID 23326332, 2013).
familial pulmonary arterial hypertension (1 paper, 2019). "Inactivation or decreased expression of BMPR2 has a well-characterized association with familial pulmonary arterial hypertension, an effect which may be due to the role of BMPR2 in suppressing the response to TNF-mediated GM-CSF release." (PMID 31780722, 2019).
fasciolosis (1 paper, 2014). "TNF-α might play a role in accelerated worm expulsion through Th2 immune response enhancement and IFN-γ production suppression may mediate parasite survival in fasciolosis." (PMID 25122166, 2014).
gallbladder polyps (1 paper, 2016). "Our previous study demonstrated that the level of TNF-α in the bile of GBC patients was significantly higher than that in patients with cholesterol gallbladder polyps." (PMID 26992854, 2016).
gallbladder tumor (1 paper, 2014). "Thus, on the basis of our findings and those of previous studies, tumor-derived TNF-α may play an important role in gallbladder tumor cell proliferation and invasion." (PMID 24676340, 2014).
gastric MALT lymphoma (1 paper, 2021). "The majority of CagY-specific T cells in gastric MALT lymphoma produced IFN-γ and TNF-α." (PMID 34502367, 2021).
gastrointestinal allergy (1 paper, 2020). A allergic disease that involves the digestive tract. "TNF-α is involved in pathophysiology of gastrointestinal allergy by initiating the process of increased intestinal permeability." (PMID 33003355, 2020).
gastrointestinal bleeding (1 paper, 2024). "Therefore, we aimed to investigate the role of seven variants in the TNF-α, IL-β, and IL-1RN genes in association with the risk of upper gastrointestinal bleeding in users of low-dose acetylsalicylic acid for the prevention of cardiovascular events." (PMID 39194098, 2024).
Gastrointestinal dysmotility (1 paper, 2017). Abnormal intestinal contractions, such as spasms and intestinal paralysis, related to the loss of the ability of the gut to coordinate muscular activity because of endogenous or exogenous causes. "To investigate whether the gastrointestinal dysmotility and the neuroplastic changes of the ENS were associated with an inflammatory process triggered by HSV-1 exposure, we evaluated the gut level of two relevant pro-inflammatory cytokines (TNF-α and IL-1β) using ELISA." (PMID 28732069, 2017).
gastrointestinal stromal tumor (1 paper, 2021). "Administration of imatinib after agonistic anti-CD40 antibody activated TAMs, redirected TAMs to antitumor M1 phenotype, by increased TNF and IL-6 production through the NFκB pathway along with decreased IL-10 production in mouse model of gastrointestinal stromal tumor GIST." (PMID 34209679, 2021).
genital warts (1 paper, 2013). "Due to the risk of potential exacerbation of genital warts, patients should be informed and perhaps screened prior to initiation of anti-TNF therapy." (PMID 24368947, 2013).
giant cell tumor (1 paper, 2012). A benign, intermediate, or malignant tumor that arises from the bone or soft tissue. "Key words: Giant cell granuloma, giant cell tumor, multinucleated giant cells, jaw, TNF-alpha, IL-6, IL-1beta,immunohistochemistry." (PMID 22157665, 2012). "The osteoclastogenic cytokines TNF-α, IL-6 and IL-1β have been investigated in giant cell tumors (GCTs) of long bones." (PMID 22157665, 2012).
GM1 gangliosidosis (1 paper, 2023). A rare lysosomal storage disorder characterized biochemically by deficient beta-galactosidase activity and clinically by a wide range of variable neurovisceral, ophthalmological and dysmorphic features. "The brains of Glb1−/− and Glb1+/− mouse models of GM1 gangliosidosis have shown activated subsets of Mφs and microglial cells and the massive production of IL1β and TNFα." (PMID 37189685, 2023).
granulocytosis (1 paper, 2014). "Although in vitro TNF inhibits hematopoiesis, chronic inflammation in RA can be associated with monocytosis and granulocytosis, and TNF induces production of pro-myelopoietic factors like G-CSF and GM-CSF." (PMID 25504080, 2014).
granulosa cell tumor (1 paper, 2015). A slow-growing, malignant tumor, characterize by the presence of granulosa-like cells and Call-Exner bodies, that is almost always found in the ovary. "KGN cultures established from human granulosa cell tumor were treated with various concentrations of AICAR or metformin prior to the addition of TNF-α." (PMID 25889494, 2015).
Hailey-Hailey disease (1 paper, 2024). Benign chronic familial pemphigus of Hailey-Hailey is characterized by rhagades mostly located in the armpits, inguinal and perineal folds (scrotum, vulva). "Tumor necrosis factor-alpha inhibitors have been used to treat and maintain remission in recalcitrant Hailey-Hailey disease patients, but additional reporting and studies are required." (PMID 39295647, 2024).
hand dermatitis (1 paper, 2023). "The tumor necrosis factor (TNF) α-238A allele has a protective effect against irritant hand dermatitis, while the TNFα-308A allele is a risk factor for irritant hand dermatitis." (PMID 36983235, 2023).
hemosiderosis (1 paper, 2024). Accumulation of iron in internal organs. "Hemosiderosis may not be reversible, serving as a permanent trigger for immune and synovial cells to induce the production of IL-1 and TNF as well as fibroblast proliferation leading to tissue hyperplasia." (PMID 39619606, 2024).
hepatobiliary tumors (1 paper, 2025). "Some randomized trials have tested probiotics in hepatobiliary tumors and have shown an increase in TNFα and IL1β in the postoperative period, supporting the use of probiotics to modulate the immune response and reduce infectious complications in patients." (PMID 40310432, 2025).
heroin addiction (1 paper, 2023). "The results of this study show that different polyphenols target specific behavioral domains of heroin addiction in a CPP model and modulate the increase in striatal inflammatory cytokines TNF-α and IL-6 observed during naloxone-precipitated heroin withdrawal." (PMID 37112606, 2023).
herpangina (1 paper, 2021). "EV-A71 infection induced interferon, pro-inflammatory cytokines and chemokines, including IFN-β, IL-6, CCL5, and TNF-α in tonsillar epithelial cells, which may play a critical role in EV-A71-caused herpangina." (PMID 33481814, 2021).
herpetic keratitis (1 paper, 2024). "Another lab reported that mice exposed to polluted air developed a severe form of herpetic keratitis with increased corneal opacity, neovascularization, and production of TNF-α, IL-1β, IFN-γ, and CCL2." (PMID 38928968, 2024).
Hirschsprung disease (1 paper, 2023). Hirschsprung disease (HSCR) is a congenital intestinal motility disorder that is characterized by signs of intestinal obstruction due to the presence of an aganglionic segment of variable extent in the terminal part of the colon. "Hirschsprung’s disease appears to induce a shift in M1 macrophages towards a proinflammatory state, leading to an increase in the production of tumor necrosis factor alpha (TNFa)." (PMID 37759758, 2023).
homocystinuria (1 paper, 2021). An autosomal recessive inherited metabolic disorder caused by mutations in the CBS, MTHFR, MTR, and MTRR genes. "Proinflammatory cytokines other than IL-6, namely IL-1α, IL-1β and TNF-α, are increased in a mouse model of homocystinuria and a range proinflammatory cytokines and chemokines [IL-1α, IL-6, TNF-α, IL-17, IL-12 (p70), MIP-1α and MIP-1β] are also elevated in homocystinuria patients." (PMID 34251022, 2021).
hyper-IgM syndrome (1 paper, 2023). A primary immune deficiency disorder characterized by defective CD40 signaling; via B cells affecting class switch recombination (CSR) and somatic hypermutation. "The structural model of CD40LG indicated that all mutations caused the X-linked hyper-IgM syndrome with pulmonary alveolar proteinosis to be located within the tumor necrosis factor homology domain." (PMID 37173671, 2023).
hypereosinophilic syndrome (1 paper, 2018). Hypereosinophilic syndrome (HES) constitutes a rare and heterogeneous group of disorders, defined as persistent and marked blood eosinophilia and/or tissue eosinophilia associated with a wide range of clinical manifestations reflecting eosinophil-induced tissue/organ damage. "For example, eosinophils stimulated with CCL11/eotaxin-1 or tumor necrosis factor alpha (TNF-α) show increased numbers of cytoplasmic EoSVs as well as do naturally activated eosinophils from patients with hypereosinophilic syndrome when compared to normal donors." (PMID 30619361, 2018).
Hyperoxaluria (1 paper, 2022). Increased excretion of oxalates in the urine. "Previous studies performed by our group in a hyperoxaluria model also demonstrate higher TNFα expression in the renal cortex." (PMID 35954150, 2022). "In order to assess the inflammatory response elicited by hyperoxaluria in preglomerular arteries, RT-PCR was performed to assess the expression of NFκB1, MCP1, and TNFα." (PMID 35954150, 2022).
Hypervolemia (1 paper, 2023). An increase in the amount of intravascular fluid, particularly in the volume of the circulating blood. "Thus, there are some arguments as to why hypervolemia could be associated with elevated TNF-α-mediated effects in HD." (PMID 38139378, 2023). "Regarding the inflammatory nature exerted by hypervolemia in HD, we examined the mRNA expression of proinflammatory genes TNF-α and IL-6 in PBMCs." (PMID 38139378, 2023). "Regarding TNF-α, this cross-sectional study provides no indications that hypervolemia may cause relevant differences in normo- and hypervolemic patients." (PMID 38139378, 2023).